NOP2 (NOP2 nucleolar protein)
Diseases named in the same sentence as NOP2 in open-access papers (continued):
Sharing a sentence is not in itself a finding about the gene and the disease.
lung carcinoma (3 papers, 2023 to 2025). "In summary, these findings collectively suggest an upregulation of NOP2 in lung cancer, and elevated NOP2 expression is associated with a poorer prognosis." (PMID 39013911, 2024). "Overexpression of NOP2 caused substantial augmentation of the invasion of lung cancer cells compared with the respective control groups." (PMID 39013911, 2024). "The results showed that the decrease in EZH2 expression triggered by NOP2 knockdown as well as the antitumor phenotype of lung cancer cells were suppressed by overexpression of ALYREF." (PMID 39013911, 2024). "The results revealed a significant upregulation of NOP2 in both lung cancer cells and tissues, and a higher expression of NOP2 was indicative of a poorer prognosis in lung cancer patients." (PMID 39013911, 2024). "Overall, these findings imply that the expression of NOP2 exerts a positive influence on the advancement of lung cancer cells in vitro." (PMID 39013911, 2024). "These discoveries unveil a novel regulatory pathway through which NOP2 exerts its oncogenic influence—at least in part by upregulating EZH2 expression in lung cancer." (PMID 39013911, 2024). "In contrast, knockdown of NOP2 effectively inhibited the growth and metastasis of lung cancer cells." (PMID 39013911, 2024). "In this study, we observed an upregulation of NOP2 in lung cancer tissues compared with normal tissues." (PMID 39013911, 2024). "To delve deeper into the regulatory mechanisms underlying lung cancer progression, we identified EZH2 as a downstream target of NOP2 through RNA-sequencing and bioinformatics analysis." (PMID 39013911, 2024). "Taken together, these findings suggest that NOP2 can promote the development of lung cancer in vivo by regulating EZH2." (PMID 39013911, 2024). "The results revealed that the majority of lung cancer cell lines exhibited elevated levels of NOP2 mRNA compared with normal human epithelial cells BEAS-2B." (PMID 39013911, 2024). "To investigate the molecular mechanism through which NOP2 influences the progression of lung cancer, we utilized RNA-sequencing analysis." (PMID 39013911, 2024). "In summary, our investigation disclosed the upregulation of NOP2 in lung cancer, correlating it with unfavorable prognosis." (PMID 39013911, 2024). "In contrast, knockdown of ALYREF inhibited the elevation of EZH2 expression triggered by NOP2 overexpression as well as the enhancement of the migratory invasive ability of lung cancer cells." (PMID 39013911, 2024). "Here, we conducted a series of in vitro and in vivo experiments to systematically characterize the biological role of NOP2 and its possible molecular mechanisms in lung cancer." (PMID 39013911, 2024). "Next, we performed cellular immunofluorescence (IF) experiments and similarly demonstrated the promotional effect of NOP2 for EMT in lung cancer cells." (PMID 39013911, 2024). "Collectively, these results demonstrate that NOP2 promotes lung cancer progression by upregulating EZH2 expression, and this promoting effect can be offset by the absence of EZH2." (PMID 39013911, 2024). "As anticipated, the overexpression of NOP2 facilitated the in vivo growth of lung cancer cells, whereas the introduction of sh-EZH2 mitigated this promoting effect." (PMID 39013911, 2024). "Subsequently, an extensive investigation was conducted to assess the expression of NOP2 at both the transcript and protein levels in human lung cancer cell lines and normal lung samples." (PMID 39013911, 2024). "Functional experiments showed that NOP2 promoted migration and invasion of lung cancer cells in vitro, thereby enhancing tumor growth and progression in vivo." (PMID 39013911, 2024). "NOP2 expression was further evaluated in four distinct lung cancer cell lines through immunoblotting." (PMID 39013911, 2024). "In contrast, upon knockdown of NOP2, a significant inhibition of the invasion of lung cancer cells was observed in comparison with the corresponding control groups." (PMID 39013911, 2024).
lung carcinoma (continued). "Our findings offer new perspectives on the molecular mechanisms of epigenetic alterations in lung cancer carcinogenesis and suggest that NOP2 may be a potential therapeutic target in lung cancer." (PMID 39013911, 2024). "However, the functional and molecular mechanisms by which NOP2 regulates lung cancer are still largely elusive." (PMID 39013911, 2024). "Consequently, to elucidate the potential role of NOP2 in lung cancer cells, we initially conducted overexpression of NOP2 in H358 and H1650 cells, and suppressed NOP2 in A549 and H1299 cells." (PMID 39013911, 2024). "Notably, we present novel evidence that NOP2 promotes lung cancer progression by enhancing EZH2 expression through an m5C-dependent mechanism." (PMID 39013911, 2024). "Altogether, our findings further confirm the oncogenic role of NOP2 in lung cancer." (PMID 39013911, 2024). "Notably, the NOP2/EZH2 axis facilitated the malignant phenotype of lung cancer cells by inducing epithelial–mesenchymal transition (EMT) both in vitro and in vivo." (PMID 39013911, 2024). "Moreover, lentivirus-mediated overexpression of NOP2 in vitro resulted in enhanced migration and invasion capabilities of lung cancer cells, while in vivo experiments demonstrated its ability to promote the growth and metastasis of xenograft tumors." (PMID 39013911, 2024). "Therefore, our hypothesis posits EZH2 as a potential target of NOP2 in lung cancer cells, with NOP2 promoting lung cancer progression through the regulation of EZH2 expression." (PMID 39013911, 2024). "Overall, NOP2 altered the expression of EZH2’s downstream target E-cadherin by regulating EZH2 expression and H3K27me3 mediated by EZH2, and thus promoted EMT in lung cancer cells." (PMID 39013911, 2024). "Here, we found that NOP2 and ALYREF had a co-regulatory role in the stability of EZH2 mRNA in lung cancer." (PMID 39013911, 2024). "Consequently, NOP2 may represent a promising therapeutic target for lung cancer treatment." (PMID 39013911, 2024). "In a word, our research highlights the significant role of NOP2 in LUAD and offers novel mechanistic insights into the NOP2/ALYREF/EZH2 axis, which holds promise as a potential target for lung cancer therapy." (PMID 39013911, 2024). "To investigate whether NOP2 regulates cell proliferation of lung cancer cells, we conducted CCK-8, EdU, and colony-formation assays to determine the proliferation changes of lung cancer cells." (PMID 39013911, 2024). "In addition, NOP2 was found to play a crucial role in promoting lung cancer progression by enhancing the stability of EZH2 mRNA in an m5C-dependent manner, thereby facilitating epithelial–mesenchymal transition (EMT) in lung cancer cells." (PMID 39013911, 2024). "However, in our study, NOP2 did not affect the proliferative capacity of lung cancer cells." (PMID 39013911, 2024).
renal clear cell carcinoma (3 papers, 2021 to 2024). "The purpose of this study was to investigate the prognostic roles of NOP2 in renal clear cell carcinoma (ccRCC) for overall survival (OS) and its relationships with immunity." (PMID 34334108, 2021). "However, the specific functions and potential mechanisms of m5C, especially involving NOP2, in clear-cell renal cell carcinoma (ccRCC), remain unclear." (PMID 39309431, 2024).
renal carcinoma (2 papers, 2021 to 2025). A carcinoma arising from the epithelium of the renal parenchyma or the renal pelvis. "Analysis of NOP2-related data in ccRCC from The Cancer Genome Atlas (TCGA) indicates that NOP2 is highly expressed in renal cancer, showing a significant correlation with poor prognosis." (PMID 40809690, 2025).
renal cell carcinoma (2 papers, 2025 to 2026). "NOP2, NSUN2, and NSUN5 mRNA were significantly upregulated in renal cell carcinoma cell lines (786-O, Caki-1) compared to a human tubular epithelial immortalized cell line (HK-2), while NSUN4 was downregulated in the renal carcinoma cell lines." (PMID 41462962, 2025). "Furthermore, NOP2, NSUN2, and NSUN5 mRNA were significantly upregulated in renal cell carcinoma tissue, while NSUN4 mRNA was downregulated." (PMID 41462962, 2025).
Sepsis (2 papers, 2023 to 2025). Sepsis is defined as life-threatening organ dysfunction caused by a dysregulated host response to infection. "Genes associated with hub RMGs may linked to the progression of sepsis, NOP2 and NAT10 were co-expressed, and previous research reported that NAT10 improves the survival and ameliorates lung injury in septic mice by inhibiting neutrophil pyroptosis." (PMID 37701433, 2023). "Overall, NSUN7, NOP2, PUS1, PUS3, and FTO were identified as important diagnostic markers for sepsis." (PMID 37701433, 2023). "Finally, by using machine learning, we identified five hub RMGs (NSUN7, FTO, NOP2, PUS1, and PUS3), which showed efficient diagnostic value of sepsis." (PMID 37701433, 2023). "To predict the occurrence of sepsis, we constructed a nomogram model for diagnosing sepsis based on the expression levels of five hub RMGs (NSUN7, FTO, NOP2, PUS1 and PUS3)." (PMID 37701433, 2023). "NOP2 and NSUN6 are both RNA methyltransferases that affect the cell cycle and proliferation activities and show high levels in carcinoma and sepsis and even provide new potential therapeutic approaches for preventing depression." (PMID 40405297, 2025). "Firstly, we determined the genes expression in PBMCs by qRT-PCR analysis, and found the expression of NSUN7, NOP2, PUS1 and PUS3 in septic patients (septic shock and sepsis) at day 1 were significantly higher than in healthy volunteers, and FTO expression was lower in septic patients." (PMID 37701433, 2023). "Notably, the expression of NOP2 and PUS1 was concurrently increased in patients with sepsis of group C3 in the integrated gene expression matrix, which was consistent with the results observed in our clinic samples." (PMID 37701433, 2023). "In addition, we identified that five RMGs (NSUN7, NOP2, PUS1, PUS3 and FTO) could function as biomarkers for clinic diagnose of sepsis." (PMID 37701433, 2023).
serous ovarian cancer (2 papers, 2024 to 2025). "NOP2 is significantly upregulated in high-grade serous ovarian cancer tissues." (PMID 41462962, 2025). "Experimental research has demonstrated that NOP2 promoted cell proliferation in vivo and in vitro through RAPGEF4, and enhanced the migration and invasion ability of high-grade serous ovarian cancer cells in vitro." (PMID 41462962, 2025).
viral infection (2 papers, 2020 to 2023). "Here, we summarize the latest findings concerning the roles of m5C RNA methyltransferases, namely, NOL1/NOP2/SUN domain (NSUN) proteins and DNA methyltransferase 2/tRNA methyltransferase 1 (DNMT2/TRDMT1) during viral infections." (PMID 33142933, 2020).
acute lymphoblastic leukemia (1 paper, 2025). Leukemia with an acute onset, characterized by the presence of lymphoblasts in the bone marrow and the peripheral blood. "The NOP2 rs3764909 and NSUN4 rs10252 variants enhanced the risk of acute lymphoblastic leukemia in children and are considered potential biomarkers of pediatric acute lymphoblastic leukemia." (PMID 41462962, 2025).
autosomal-recessive intellectual disability (1 paper, 2024). "Loss-of-function mutations in NOP2/Sun RNA MT2 and MT6 (NSUN2 and NSUN6, respectively) have been identified as the cause of autosomal-recessive intellectual disability (ID) in humans." (PMID 38550277, 2024).
leukoplakia (1 paper, 2021). A white patch or plaque on a mucous membrane that cannot be characterized clinically or pathologically as any other disease. "The expression of three m5C regulators—NOP2, DNMT3B, and ALYREF—was upregulated in oral leukoplakia patients from two microarray datasets, GSE26549 and GSE85195." (PMID 34957065, 2021).
myeloid leukemia (1 paper, 2021). A clonal proliferation of myeloid cells and their precursors in the bone marrow, peripheral blood, and spleen. "Our study demonstrated a marked increase in NOP2/NSUN1 and NSUN2-mediated m5C in drug (5-azacitidine) resistant myeloid leukemia cells." (PMID 33922187, 2021).
osteoporosis (1 paper, 2021). A condition of reduced bone mass, with decreased cortical thickness and a decrease in the number and size of the trabeculae of cancellous bone (but normal chemical composition), resulting in increased fracture incidence. "In addition, we obtained differentially expressed miRNAs between osteoporosis and controls, and identified the regulatory relationship between differentially expressed hsa-miR-3130-5p and NOP2 by TargetScan." (PMID 33778083, 2021). "Compared with the control group, HIST1H3G, NOP2, OXA1L, and ZFPM2 were upregulated in osteoporosis, and MAP3K5 was downregulated." (PMID 33778083, 2021).
prostate adenocarcinoma (1 paper, 2022). "NOP2 has been found to be upregulated in several cancer types, including lung adenocarcinoma (LUAD), leukemia, breast-invasive carcinoma (BRCA), and prostate adenocarcinoma (PRAD), and, therefore, considered to be a predictive cancer marker." (PMID 35372330, 2022).
Stroke (1 paper, 2022). Sudden impairment of blood flow to a part of the brain due to occlusion or rupture of an artery to the brain. "Furthermore, the expression of NSUN1, alternatively known as NOP2, was increased in adult neural stem cells after stroke and was positively correlated with adult neural stem cell proliferation, suggesting a potential role for NSUN1 in promoting recovery after stroke." (PMID 35350378, 2022).
tumor (43 papers, 2017 to 2026). "To further elucidate the underlying molecular mechanism by which NOP2 exerts tumor-promoting effects in ccRCC, we performed RNA sequencing (RNA-seq) and m5C bisulfite sequencing (Bis-seq) on 786-O cells with NOP2 knocked down (siNOP2) and control cells (siNC)." (PMID 39309431, 2024). "Our results showed that NSUN2, DNMT1, DNMT3A, DNMT3B, TRDMT, and ALYREF were related to high or low tumor risk, while NOP2 was related to the pTNM stage of tumors." (PMID 38579085, 2024). "Functionally, NOP2 promoted cell proliferation and invasion, enhancing tumor growth in xenograft models." (PMID 42088435, 2026). "NOP2 (also known as NSUN1), a nucleolar RNA methyltransferase involved in ribosomal RNA methylation and ribosome biogenesis, has been reported to promote tumor progression in several individual malignancies." (PMID 42136761, 2026). "NOP2 knockdown combined with sorafenib increases sorafenib sensitivity, significantly inhibiting tumor growth." (PMID 39802639, 2025). "GEPIA2 database analysis results show that COAD and READ tumor tissues have higher NOP2 levels than normal tissues." (PMID 40366008, 2025). "Combining NOP2 knockout and sorafenib enhanced sensitivity to sorafenib, significantly inhibiting tumor growth." (PMID 41462962, 2025). "NOP2 expression is elevated in GC tissue, where high NOP2 expression is significantly correlated with tumor size, invasion depth, and lymph node metastasis." (PMID 41462962, 2025). "The silencing of NOP2 significantly decreased the tumor growth, tumor volume, and tumor weight during 21 days of treatment." (PMID 40366008, 2025). "In vivo experiments also confirmed that silencing of NOP2 inhibited tumor growth, metastasis, as well as LMNB2 expression." (PMID 40366008, 2025). "We found high expression of NOP2 was related to tumor proliferation and JAK-STAT pathways and also responded to JAK inhibitors in multiple cancer types." (PMID 39160604, 2024). "Previous research suggests that NOP2 is expressed at higher levels in human malignant tumor cells and is considered as a prognostic marker for cancer aggressiveness." (PMID 37701433, 2023). "Taken together, the results strongly suggest that c-Myc promotes tumor progression by acting as a downstream target of NOP2." (PMID 37398932, 2023). "IHC analysis indicated that compared with the NOP2-KO group, the tumor tissue of the WT group showed higher NOP2 expression." (PMID 37398932, 2023). "NOP2 knockout in combination with sorafenib enhanced sorafenib sensitivity, which, in turn, led to marked tumor growth inhibition." (PMID 37398932, 2023). "Representative gross pictures and tumor growth curves showed that tumor growth of the NOP2-KO group was markedly slower than that of the WT group." (PMID 37398932, 2023). "Tumor xenograft in nude mice revealed that c-Myc overexpression partly rescued the inhibitory effects of NOP2 knockdown on the growth rate in vivo." (PMID 37398932, 2023). "The excellent tumor suppressor effect of NOP2 KO in PDX models indicates the immense potential of NOP2 activity inhibition in clinical therapeutic development." (PMID 37398932, 2023). "METL14 is under-expressed in ccRCC tissues, and NOP2 expression is higher in tumor tissues than in normal tissues." (PMID 35571068, 2022). "There were significant differences in NOP2 expression in different tumor stages of some cancers, such as ACC, BLCA, KICH, KIRC, KIRP, LIHC, and LUAD." (PMID 35372330, 2022). "A trend was also observed that the later the tumor stage, the higher the expression of NOP2, especially in ACC and KIRC." (PMID 35372330, 2022). "In human tumor cells, NOP2 is shown to combine with the telomerase RNA component (TERC) via its rRNA methyltransferase domain, thereby activating and regulating cyclin D1 gene transcription, which maintains cell proliferation." (PMID 35562754, 2022).